TNF (tumor necrosis factor)
Diseases named in the same sentence as TNF in open-access papers (continued):
Sharing a sentence is not in itself a finding about the gene and the disease.
tumor (continued). "In view of the relevance of TRAF2 and the cIAPs to protect from TNFR1-induced cell death (see Section 3.1), this suggested that the sensitivity of tumor cells for TNF cytotoxicity is a crucial factor for ICB efficacy." (PMID 36011046, 2022). "Apart from immune cells, tumor cells also secrete various cytokines such as TNF、GM-CSF、IL-6、IFN-γand MCP-1." (PMID 36530985, 2022). "Tumor perfusion in HCC was dramatically improved after daily intravenous (i.v.)injection of 5 μg TNFα-CSG for five consecutive days." (PMID 35273916, 2022). "The amounts of IL-6 and TNF-α in tumor supernatants were 3.5-7.5 times and 5-6 times higher, respectively, compared to the corresponding levels of these cytokines in the blood." (PMID 36330464, 2022). "The first was inflammation-related pathways, such as the IL6/JAK/STAT3 signalling, inflammatory response, IL2/STAT5 signalling, TNF-alpha signalling via NFKB, and KRAS signalling pathways, which have been proven to be associated with tumours." (PMID 35246158, 2022). "Subsequently, these C3a-activated astrocytes promote MB tumor progression both in vitro and in vivo through TNF-α secretion." (PMID 36291792, 2022). "Lymphocytes are a major component of anti-tumor immunity, stimulating the release of cytokines such as interferons and TNF-α, thereby exerting protective effects." (PMID 35557848, 2022). "The potent pro-inflammatory cytokine tumor necrosis factor α (TNFα) has been connected to cancer progression and treatment ever since its discovery as a major factor contributing to the anti-tumor activities of Coley’s toxins." (PMID 35663982, 2022). "Meanwhile, up-regulated expression of ERβ, a tumor suppressor, and ERβ-mediated accumulation of TNFα were also observed in TNBC MDA-MB-231 cells." (PMID 35593465, 2022). "The immunohistochemistry results revealed that the mice after WJR treatment had higher densities of IL-10, IFN-γ, and TNF-α than the NC group in the tumor tissue." (PMID 36212428, 2022). "Among all of them, the tumor-promoting functions related to the actions of TNF-α, an important promoter of the mesenchymal epithelial transition phenomenon, should be highlighted." (PMID 36361889, 2022). "TNFα is a major pro-inflammatory cytokine named after the observation that it induces rapid hemorrhagic necrosis in tumors at high dose, mediating tumor shrinkage." (PMID 35269922, 2022). "After combination treatment, CD62L shedding, increased expression of CD107a in T cells, as well as the elevated IFN-γ and TNF-α level partly account for the significant tumor growth inhibition." (PMID 35688951, 2022). "TNF is an endogenous tumor promoter because of its stimulatory effects on cancer cell growth, proliferation, invasion, metastasis, and tumor angiogenesis." (PMID 36230879, 2022). "In contrast, accumulating evidence has shown that both cancer cells and the tumor microenvironment produce TNF in an autocrine or paracrine manner." (PMID 35844550, 2022). "TNF-α also contributes to tumor initiation by stimulating the production of genotoxic molecules such as nitric oxide (NO) and ROS." (PMID 35493517, 2022). "COR inhibited tumor growth and elongated survival time of tumor-bearing mice by regulating the expression of cytokines such as IL-2, IL-4, TNF-α, TGF-β and IFN-γ." (PMID 35200422, 2022). "NGR-based peptides have been used to deliver the cancer drug DOX, apoptotic peptides, and cytokines such as the tumor necrosis factor for transporting the tumor or tumor vasculature and augmenting the therapeutic efficacy." (PMID 35890297, 2022). "PCR results showed that HPP promoted the expression of IL-1β, IL-6 and TNF-α mRNA in macrophages in the tumor microenvironment." (PMID 35603205, 2022). "Other cytokines, such as IL-17, IL-22, tumor necrosis factor α (TNFα), and IL-6, are involved in tumor promotion." (PMID 35582541, 2022). "As a critical pro-inflammatory cytokine in the tumor microenvironment, TNF-α is mainly secreted by macrophages and tumor cells." (PMID 35965509, 2022).
tumor (continued). "In cancer immunotherapy, TNF-α acts as a mediator of anti-tumor immune responses and several immunotherapies have shown reduced anti-tumor activity in the presence of TNF-α antagonists." (PMID 35327456, 2022). "TNF-α triggers and amplifies acute inflammatory reactions with characteristics of rubor, calor, dolor, and tumor." (PMID 35215138, 2022). "The main difference in the generation of mature DCs in our work is an additional application of TNF-α and tumor oligopeptides MUC 1.1, MUC 1.2, MAGE A.310–12." (PMID 35589776, 2022). "The expressions of serum CXCL13, ICAM-1, MCP-5, IL-7, and TNF-α in tumor-bearing mice treated with rAd-mIL-28B were lower compared to rAd-EGFP-treated mice (P < 0.05)." (PMID 35935577, 2022). "As the RGR peptide has been used for the tumor-targeted delivery of tumor necrosis factor α, we attempted to improve the tumor-homing ability of TRAIL by fuzing RGR to the N-terminus of TRAIL." (PMID 35635308, 2022). "To understand the mechanism by which XFZYD inhibits RasV12/lgl−/−-induced tumour growth and invasion, we considered TNF/JNK and caspase signalling as putative central targets." (PMID 35903326, 2022). "One anti-tumor mediator uniquely prestored and released from MCs through FcεRI stimulation is TNF-α." (PMID 35740607, 2022). "Interferon-γ is well-known to contribute to the CART cells’ cytotoxicity by targeting and destroying the tumor stroma, while TNF-α has been shown to sensitize tumor cells themselves for getting killed by CD8+ T cells." (PMID 36700229, 2022). "TNF-α is known to induce cell death and to control cell proliferation within certain limits, preventing or controlling the genesis of tumor cells." (PMID 35432496, 2022). "Many cytokines (e.g., INF-γ, TNF-α, IL-17, and IL-12) and tumor-derived exosomes in the TME can induce PD-L1 expression and cause tumor immune escape." (PMID 36313280, 2022). "Some models of breast cancer in mice have shown that pDCs alone can kill tumor cells through the expression of TNF, as well as promoting the activation of NKs." (PMID 35267487, 2022). "AAV-Bevacizumab in combination with AOaV-1 led to a significant increase in the number of tumor-specific TNF-α+IFN-γ+CD8+ T cells, which have previously been shown to be a beneficial subset in cancer immunotherapies." (PMID 35203573, 2022). "PRKCDBP was a downstream target of TNF α-induced tumor cell apoptosis signaling, and was activated by NF-κB." (PMID 35224960, 2022). "At last, the moDCs were derived from monocytes and produced pro-inflammatory cytokines, including TNF, IL-12, and IL-6, to promote tumor progression." (PMID 35585567, 2022). "Monocytes from PBMCs were cultured in a medium with GM-CSF and IL-4; pulsed with Keyhole Limpet Hemocyanin (KLH) and autologous tumor cell lysate in the presence of GM-CSF and TNFα." (PMID 36011029, 2022). "Virotherapy has the potential to significantly boost the infiltration of CD4+ and CD8+ T lymphocytes as well as the release of IFN-γ and TNF-α in tumor tissues." (PMID 36703982, 2022). "Data from preclinical studies hint that TNF neutralization in combination with ICIs reduces clinical irAE and improves antitumor efficacy in tumor models." (PMID 35844493, 2022). "Regarding the ADP@SWNT/TNFα+laser irradiation group, a high scathe level was observed, and the tumor size decreased with heat ambustion on the skin." (PMID 34994069, 2022). "After the treatment, positive correlations of mSWAT with the levels of IL22, IL33, and TNF-α in the tumor tissue were found." (PMID 35237320, 2022). "Other cytokines, such as TGF-β, TNF-α, IL-1β, IL-8, and IL-11 can also promote the retrodifferentiation of tumor-derived hepatocytes into stem/progenitor cells." (PMID 35449193, 2022). "Following in vitro stimulation with immunodominant peptides, the CMV-specific CD8+ T cells reverse their competent cytolytic function to release several cytokines, including TNF-α and IFNγ that are involved in several anti-tumor immune responses." (PMID 35515137, 2022).
tumor (continued). "Proinflammatory cytokines, such as interleukin (IL)-1 which influences the tumour microenvironment and promotes cancer initiation and progression and TNF-α which stimulates cancer cell growth, proliferation, invasion and metastasis, and tumour angiogenesis." (PMID 36551617, 2022). "TNF-α promotes cancer cell proliferation, migration, and adhesion in the tumor microenvironment, accelerating multistep cancer development." (PMID 35612292, 2022). "Armed virus Ad5/3-D24-hTNFa produced TNFα in tumors, reduced tumor growth and improved survival relative to control virus in a PC-3 MM2 xenograft murine model of prostate cancer." (PMID 35155581, 2022). "Cytotoxic T lymphocytes (CTLs) are the central effector cells in antitumor responses, as they specifically kill mutant cells or tumor cells through the granzyme/perforin pathway and death receptor pathway (TNF-TNFR and Fas-Fasl pathways)." (PMID 35909469, 2022). "In our study, eNK-EXO treated eNK cells and NK92 cells showed enhanced tumor-killing activity and increased release of TNF-α and perforin." (PMID 36741396, 2022). "Herein, DOX-PRNP2 ameliorated the elevated tumor levels of IL-6, TNF-α and VEGF more efficiently than free DOX." (PMID 35269343, 2022). "An amount of TNFα in human blood serum was negatively correlated with proliferation of tumor cells; however, increased circulating TNFα was associated with poor overall and cancer-specific patient survival." (PMID 36555251, 2022). "TNF is primarily produced by mononuclear macrophages and can prevent the body from the infringement by killing tumor cells." (PMID 35837376, 2022). "The TnT-specific adhesion of FcεRI-activated MCs to tumor cells was characterized by the transport of the MC granule content into the tumor cells, including tryptase and TNF-α." (PMID 35740607, 2022). "Serial measurement of changes in blood flow inside the same tumor confirmed the castration-induced reduction of blood flow was acutely TNF dependent." (PMID 36551505, 2022). "The M1 phenotype is activated by Toll-like receptor ligands, and interferon gamma (IFN-γ), produces tumor cytotoxicity by producing pro-inflammatory cytokines such as TNF-α and IL-1β, and inhibits tumor progression." (PMID 35740547, 2022). "ATP directly acts on the P2X7 receptor, activating the NLRP3 inflammasome in the macrophages, and further increasing the content of the inflammatory cytokines IL‐1β, IL‐18, and TNF‐α, ultimately leading to tumor regression." (PMID 35522104, 2022). "The anticancer potential of the spiro-acridine compounds was associated with antiangiogenic action and up-regulation of Th1-type responses, mainly by inducing the increase of TNF-α and IL-1β levels in the tumor microenvironment." (PMID 36324671, 2022). "Only LNT-SeNPs + TNF-α generated significant inhibition of tumor growth after 2 weeks of treatment (tumor size = 332 ± 84 mm3 vs. 755 ± 161 mm3 in the control group, p = 0.0159)." (PMID 36678748, 2022). "Upon anti-PSCA IgG4-TM mediated cross-linkage with PC3-PSCA tumor cells, UniCAR T cells were engaged for significant secretion of the pro-inflammatory cytokines TNF and IFN-γ, as well as the growth-promoting cytokine IL-2." (PMID 35454902, 2022). "In a subsequent study, the same authors analyzed the tumor expression of TNF and its regulator SPATA2 in relation to the clinical-pathological characteristics and clinical outcome of patients with endometrial carcinoma (EC)." (PMID 36402749, 2022). "CD8+ T cells, as the prime anti-tumor cells, can destroy cancerous cells by secreting perforin and granzyme B through the Fas/FasL pathway once they contact tumor cells or release IFN-γ and TNFα to eliminate tumor cells." (PMID 35069907, 2022). "A significant correlation was found between periostin levels in margin and VEGF-A, IFN-γ IL-1 β, IL-17, and TNFα in tumor and margin specimens." (PMID 35056404, 2022).
tumor (continued). "Remarkably, enrichment analysis revealed that Uba6-null tumour cells had a marked increase in gene expression profiles evoked by inflammatory cytokines, such as TNF-α, IFNα, and IFNγ." (PMID 36109526, 2022). "Tumor necrosis factor-α overproduction mediated by EBER/TLR3 pathway created a pro-tumorigenic microenvironment for tumor growth." (PMID 36551991, 2022). "Th1 cells directly kill malignant cells via release of TNF-α which activates TNF-related apoptosis-inducing ligand (TRAIL) on the tumor cell surface." (PMID 35757015, 2022). "It suggests that administration of HSA can also lead to lower tumour cells proliferation and increased apoptosis by reducing the expression these antiapoptotic factors and or proteins such as TNF-α, COX-2, and Bcl-xL." (PMID 35386216, 2022). "In there, natural killer (NK) cells can secrete cytokines, such as interferon (IFN)-gamma and tumor necrosis factor (TNF)-α, to exert an immunosuppressive phenotype via inhibiting tumor cell proliferation and tumor angiogenesis." (PMID 35237578, 2022). "We chose to activate canonical NFκB/p65 signaling with tumor necrosis factor alpha (TNFα), a potent ligand for canonical NFκB/p65 signaling known to promote proliferation, migration, and primary tumor growth of TNBC24,25." (PMID 35177654, 2022). "Tumor-infiltrating CD8+T cells are the mainstay of tumor cell killing, and these cells specifically kill tumor cells mainly through the perforin-granzyme, Fas-FasL, and TNF-TNFR pathways." (PMID 36354702, 2022). "HER2/neu IgE-sensitized MCs were activated by BT-474 cells to release TNF-α into the tumor cells at three days as detected with TNF-α -specific Abs." (PMID 35740607, 2022). "Compared with XH administration, PX exhibited a stronger antitumor effect, such as smaller tumor volume, lower interleukin 17 (IL-17), IL-6 and tumor necrosis factor-alpha (TNFα) serum levels, and higher interferon-gamma (IFN-γ) concentration." (PMID 36582768, 2022). "VEGFA and TNF are key determinants of mast cell activity with pro-tumorigenic or suppressive roles respectively and the VEGFA:TNF ratio acts as a surrogate marker of tumor progression." (PMID 36253784, 2022). "The tumor- and host-produced cytokines, such as IL-6 and TNF-α, are believed to play a significant role in the catabolism and weight loss associated with some malignant and nonmalignant conditions." (PMID 36471329, 2022). "M1 macrophages are defined by their pro-inflammatory phenotype, expressing numerous pro-inflammatory mediators, including IL-1β, IL-1α, IL-12, tumor necrosis factor (TNF)-α, which tends to inhibit tumor development." (PMID 35646637, 2022). "For instance, manipulating the tumor microenvironment by reducing tumor necrosis factor produced myeloid cells using antibiotics appeared to decrease the tumor eradication rate." (PMID 35754845, 2022). "On the other hand, the mechanisms by which TMC play a role in tumor suppression are exocytosis of granules that contain serine protease and tumor cell cytotoxicity through receptor-ligand binding through TNF-α and FasL." (PMID 36293435, 2022). "Knockdown of wgn in all muscles attenuates muscle degeneration in tumor-hosting larvae, indicating a role for TNF-α/Egr signaling in muscle wasting." (PMID 35319749, 2022). "In contrast, RPM scores were positively correlated with IFNGR1, TGF-β, and TNF-α families, which play pro-tumor roles in TIME." (PMID 35493519, 2022). "The salivary protein results showed that various inflammatory markers were higher in the saliva of tumor patients with a trend of increased IL-10, IL-4, and IL-8; MCP-1; TNF-α; and VEGF levels observed, probably linked with the disease." (PMID 34251535, 2022).
tumor (continued). "To ascertain why ESM1 is upregulated in bevacizumab-resistant tumor cells, we evaluated the effects of different concentrations of TNFα on ESM1 mRNA and protein expression in MDA-MB-231-S cells." (PMID 36428773, 2022). "By surrounding the circulating tumor, platelets assist the tumor to evade the immune system and TNF-α-mediated cytotoxicity." (PMID 35682700, 2022). "Nevertheless, many studies demonstrated the relationship between TNF-α and NF-κB and tumor development." (PMID 36139719, 2022). "The inflammatory factors IL-1β, IL-8, and TNF-α can alter the tumor microenvironment and promote tumor growth, angiogenesis, and metastasis." (PMID 35188865, 2022). "The authors supposed that cytokine release from tumor cells, including tumor necrosis factor-alpha and epidermal growth factor, can induce the maturation of epidermal keratinocytes." (PMID 36291985, 2022). "The present review is focused on the development and use of NGR-TNF, a genetically engineered derivative of tumor necrosis factor-α (TNF) that can target the tumor blood vessels and increase the permeability of the BBTB." (PMID 35890309, 2022). "The triple therapy-activated tumor-infiltrating CTLs and NK cells and increased the production of TNF-α and IL-12, resulting in a significant inhibition of tumor growth and a total absence of lung metastasis in vivo." (PMID 35335881, 2022). "There was no doubt in the results that EMT pathway was the most enriched in C2 subtype compared with other enriched tumor-related pathways such as angiogenesis, hypoxia, TNF-α signaling and TGF-β signaling." (PMID 36467998, 2022). "On the other hand, several studies have demonstrated that attenuated Salmonella enterica does not cause systemic toxicity and represents an effective and safe strategy to carry immunomodulatory molecules such as IFN-γ and TNF-α into the tumor microenvironment." (PMID 36077761, 2022). "Mice that received TNFα-treated BCSC2 cells showed dramatically accelerated tumor growth when compared to untreated cells." (PMID 36290384, 2022). "TNF-α expression has been confirmed in the tumor micro-environment in several malignancies including PCa." (PMID 35406450, 2022). "In contrast, Beff cells produce proinflammatory cytokines, including IL-6, IFNγ, and tumor TNFα, to stimulate memory and memory effector CD4+ T cell responses." (PMID 35267563, 2022). "Accordingly, in vivo treatment of the xenografts with BMS-345541 significantly inhibited TNF-induced NF-κB signaling activation in blastic cells and reduced BM tumor burden." (PMID 35241842, 2022). "TAMs (tumor-associated macrophages) show defective activation of NF-κB in the presence of TNF-α and bacterial LPS (lipopolysaccharide) and maintain the inflammatory phenotype in the tumor." (PMID 35741450, 2022). "In the tumor microenvironment, a large number of cytokines and chemokines, such as IL-1β, IL-6, IL-8, and TNFα, can also induce EMT in OSCC." (PMID 35155249, 2022). "On the cellular level, TNFα is one of the pro-tumor cytokines enhancing viability in all analyzed GSC populations." (PMID 36361720, 2022). "CD8+ CTLs can recognize abnormal cells, such as tumor cells by cooperating with helper T1 cells (Th1) and mediate antitumor immune responses by releasing perforin, granzyme, and TNF-α to damage tumor cells." (PMID 35757756, 2022). "Parallel to the analysis of BCRP expression, the changes in the levels of IL-1β, TNF-α, and IL-10 cytokines in peripheral blood in the control and tumor-bearing animals were investigated." (PMID 35053477, 2022). "Since it was first discovered cytotoxic to tumour cells and primary inducer of tumour regression in the past, TNF in recent times is perceived as the potent mediator in apoptosis." (PMID 35651608, 2022). "In the same way, TNF-α has been seen to exert a tumor-promoting role in BC progression and induce metastasis, fostering tumor escape from immune system control." (PMID 35681689, 2022).